KAT2A (lysine acetyltransferase 2A)
Diseases named in the same sentence as KAT2A in open-access papers (continued):
Sharing a sentence is not in itself a finding about the gene and the disease.
infection (3 papers, 2018 to 2026). The state of being infected such as from the introduction of a foreign agent such as serum, vaccine, antigenic substance or organism. "During SC19 infection, KAT2A protein expression was markedly reduced but its mRNA expression was not affected." (PMID 41882776, 2026). "KAT2A knockdown aggravated necroptosis and upregulated phosphorylation of RIPK1, whereas RIPK1 inhibitor Nec-1 rescued SC19-induced necroptosis, indicating that KAT2A regulates RIPK1-dependent necroptosis during SC19 infection." (PMID 41882776, 2026). "KAT2A inhibition using significantly exacerbated SC19-induced cell permeability disruption by transwell infection model." (PMID 41882776, 2026). "In addition, MCT1 knockdown via lentivirus infection of specific shRNAs remarkably abrogated the effects of reconstituting wild-type KAT2A in RCC cells (Caki-2 and A498) in which KAT2A had been knocked out, indicating that KAT2A depended on MCT1 to promote RCC proliferation." (PMID 34268311, 2021).
adenocarcinoma (1 paper, 2025). A common cancer characterized by the presence of malignant glandular cells. "As expected, xenograft tumors exhibited the typical histology of CRC adenocarcinomas, expressing the proliferation marker KI67 and partially also differentiation markers such as CDX2, particularly following KAT2A knockdown." (PMID 40140561, 2025).
genetic disorder (1 paper, 2019). "Our results go further and show that a mutation in a gene coding for a subunit of a basal transcription factor may also have an impact on the HAT activity of KAT2A in trans, leading to global alterations in chromatin structure and a human genetic disorder." (PMID 30894545, 2019).
heart disease (1 paper, 2024). "Recent reports indicate that Kat2b is a susceptibility gene for heart disease, and Kat2a is involved in the intracellular lipid accumulation observed in cardiac mesenchymal stromal cells in patients with arrhythmogenic cardiomyopathy." (PMID 39728461, 2024).
lymph node (1 paper, 2023). "Consistent with the determined mechanism, we observed that CPT1a and KAT2a proteins were highly co-expressed within lung and liver metastases compared to cranial bone and lymph node metastases." (PMID 36732635, 2023).
metabolic disease (1 paper, 2023). A congenital disorder (due to inherited enzyme abnormality) or acquired (due to failure of a metabolically important organ) disorder resulting from an abnormal metabolic process. "Previous studies demonstrated that KAT2A controlled glucose and lipid metabolic pathways and its dysfunction resulted in metabolic diseases." (PMID 37313329, 2023).
KAT2A also shares sentences with these, for which no sentence is quoted: non-small cell lung carcinoma (3 papers); colon adenocarcinoma (2); acute lung injury (1); anemia (1); atrial septal defect (1); atrioventricular septal defects (1); diffuse large B-cell lymphoma (1); esophageal cancer (1); esophageal squamous cell carcinoma (1); hepatitis B virus infection (1); immune disorder (1); kidney damage (1); liver fibrosis (1); lymphoma (1); microcephaly (1); Pan (1); pancreatic adenocarcinoma (1); rheumatoid arthritis (1); synovitis (1); triple-negative breast carcinoma (1); virus infection (1); vitiligo (1).